CD248 (CD248 molecule)
Diseases named in the same sentence as CD248 in open-access papers (continued):
Sharing a sentence is not in itself a finding about the gene and the disease.
tumor (continued). "Since the in vivo pericytes might not need to retain high levels of CD248 for an extended period of time, the tumor microenvironment might lack the supporting factors for fast replenishment of CD248, which would explain why MORAb-004 could cause a more severe reduction in vivo." (PMID 26327620, 2015). "The findings indicate that decoupling of CD248 regulation by TGFβ may contribute to its tumor-promoting properties, and underline the importance of exploring the TGFβ-CD248 signaling pathway as a potential therapeutic target for early prevention of cancer and proliferative disorders." (PMID 24555435, 2014). "By gaining further insights, one may ultimately consider therapeutic strategies to interfere with CD248 signaling pathways to "normalize", i.e. reverse the genotype/phenotype of the tumor associated fibroblast, thereby turning a tumor-permissive stromal environment into a tumor-prohibitive one." (PMID 21549007, 2011). "Overall, the preceding findings indicate that loss of CD248 or its cytoplasmic domain results in an uncoupling of the link between tumor growth and vessel density, and that alterations in stroma-derived factors regulated by CD248 may underlie the differences in tumor growth." (PMID 21549007, 2011). "It has been reported that multiple subsets of CAFs exist, among these, CD248+ mechanoresponsive CAFs represent a specific subset that localizes adjacent to the tumor nest." (PMID 40276611, 2025). "Further analysis using the Tumor Immune Single-Cell Hub (TISCH) database showed that CD248 expression was predominantly restricted to CAF populations in NSCLC samples." (PMID 40735646, 2025). "High CD248 expression played a crucial role in pan-cancer, including immune cell infiltration, tumor progression and metastasis, and patient prognosis." (PMID 40276611, 2025). "Mutations and amplifications represented the predominant form of CD248 genetic alterations in TCGA tumor samples." (PMID 40276611, 2025). "Our findings also shed light on key signaling pathways involving CD248+ CAFs that contribute to tumor immune escape and propose a potential therapeutic strategy targeting this axis for improved NSCLC treatment outcomes." (PMID 40735646, 2025). "CD248 is a type I transmembrane glycoprotein that was initially identified in tumor vascular endothelial cells." (PMID 40451785, 2025). "CD248 plays a crucial role in tumor cells’ functions, including invasion, migration, and proliferation." (PMID 40276611, 2025). "The genetic alterations of CD248 across different tumor types within the TCGA datasets were studied using cBioPortal." (PMID 40276611, 2025). "The expression pattern of CD248 mRNA across diverse tumor tissues was analyzed in the GEPIA2 Database." (PMID 40276611, 2025). "First, CD248 expression levels are heterogeneous within distinct tumor microenvironments, with elevated expression observed in tumors rich in CAFs and vascularization, such as in GBM, KIRC, and LIHC." (PMID 40276611, 2025). "Ki‐67‐positive cell quantity was markedly (p < 0.001) reduced in the conditional CD248 knockout versus WT mice, based on Ki‐67 IHC staining, indicating that the tumour cell proliferation was markedly inhibited in conditional CD248 knockout mice." (PMID 38396325, 2024). "MORAb-004, as discussed in subsequent sections, demonstrated the validity of CD248 targeting in preclinical tumor models, and has advanced to clinical trials." (PMID 38468017, 2024). "We revealed that the tumour growth in conditional CD248 knockout mice was dramatically reduced, relative to WT mice (p < 0.05)." (PMID 38396325, 2024). "CD248 is typically present within tumour stromal fibroblasts and perivascular cells, and has minimal expression within healthy regions." (PMID 38396325, 2024). "Studies revealed that antibodies that block or knock out CD248 strongly suppress tumour cell development and angiogenesis." (PMID 38396325, 2024).
tumor (continued). "Enhanced intravasation of tumor cells across endothelium into the vessel lumen via stromal CD248 expression was demonstrated to be dependent on direct contact with pericytes expressing CD248." (PMID 38468017, 2024). "Our study emphasizes the importance and potential mechanism of CD248+CAFs in NSCLC tumour metastasis and provides a new strategy for improving the survival time of NSCLC patients." (PMID 39164826, 2024). "At the same time, CD248 + mr-CAFs increased in treated tumor tissues (P < 0.05 by Wilcoxon signed-rank test)." (PMID 39334513, 2024). "Mechanistically, CD248 + mechanoresponsive CAFs approached and lined the tumor nest to physically block the infiltration of CD8 + T cells and drug delivery, while IL6 + CCL2 + immunomodulatory CAFs induced therapeutic resistance with distinct IL-6 expression." (PMID 39334513, 2024). "We demonstrated that the tumour weight of conditional CD248 knockout mice was considerably less than the WT mice (p < 0.01)." (PMID 38396325, 2024). "In a tumour lung metastasis model utilizing fibroblast‐specific CD248 gene knockout mice, CD248 gene knockout mice showed a significantly reduced ability to develop tumour lung metastasis compared to that of WT mice." (PMID 39164826, 2024). "Emerging evidences highlight CD248 as a particular bioindicator of activated fibroblasts, and this includes CAFs in tumours." (PMID 38396325, 2024). "In a model of tumour lung metastasis, we also discovered that CD248 knockout mice had a significantly reduced ability to develop lung metastases compared to wild‐type mice." (PMID 39164826, 2024). "We observed that CD248 + mr-CAFs were far from the tumor cells in naïve tissues but lined the tumor nests in treated tumor tissues, providing a physical barrier to protect malignant tumor cells from immune infiltration and drug delivery." (PMID 39334513, 2024). "CD248 is also strongly expressed in diverse sarcomas, neuroblastomas, skin cancers, breast cancers, and additional tumours." (PMID 39164826, 2024). "In contrast, a relatively small number of tumour cells infiltrated the muscle layer of the CD248‐knockout mice." (PMID 39164826, 2024). "In Lewis lung carcinoma (LLC) tumors implanted in the colon and orthotopic glioblastomas, CD248 KO tumors demonstrated significantly more small vessels (< 50um) within the tumor compared to controls." (PMID 38468017, 2024). "The immune based investigation delineated the immune characteristics of DC, and disclosed the potential actions of anti-CD248 in the Cold tumor cluster, and anti-CD276 or CAR-T/CD276 in the Hot tumor cluster, providing a clinic direction for DC." (PMID 36991000, 2023). "For example, one study reported that CD248-positive pericytes can promote the infiltration of tumor cells into blood vessels and distant metastasis in a cell-contact-dependent manner." (PMID 36997926, 2023). "IgG78 is a specific antibody targeting glycosylated CD248, which reduces the expression level of CD248 in CAFs and decreases the production of M2 macrophages, exerting anti-tumor effects." (PMID 36990999, 2023). "The high expression of CD248 by vessels in a variety of tumor types has been previously reported by several groups." (PMID 37298499, 2023). "Since this protein family has been linked to tumor development (especially CD93, CLEC14A and CD248), there is a great interest in studying these proteins as possible therapeutic targets in cancer treatment." (PMID 37443812, 2023). "Expression of human CD248 has been shown to be highly restricted close to tumor vessels, implicating CD248 as being a modulator of tumor angiogenesis." (PMID 37298499, 2023). "While the targeting effect of IgG78 on CD248 is highly correlated with the level of N-glycan on CD248, the anti-tumor effect of IgG78 is diminished when the N-glycan chain of CD248 is disrupted." (PMID 36990999, 2023).
tumor (continued). "Recent studies have indicated that stromal CD248 expression in fibroblasts and pericytes plays a role in tissue fibrosis and tumor progression." (PMID 36401329, 2022). "Stromal CD248 promotes tumor growth and metastasis, partly through an increase in tumor cell extravasation and tumor environment construction." (PMID 36401329, 2022). "CD248 has been shown to be upregulated in cancers, tumours, and many fibrotic diseases, and is considered as a therapeutic target and biomarker." (PMID 36119065, 2022). "The Cancer Genome Atlas (TCGA) data set and clinical specimens were adopted to analyze the expression of CD248 between normal and tumor tissues." (PMID 33791227, 2021). "CD248-specific siRNA was used to investigate the potential function of CD248 in CAF tumor promotion." (PMID 34970489, 2021). "Once CD248 is knocked out in mice, there was a striking reduction in the growth of the tumors, invasiveness, and metastasis after tumor transplantation, indicating that CD248-positive stroma would promote malignancy." (PMID 33791227, 2021). "In the TCGA cohort, we compared CD248 expression between normal (n = 128) and tumor (n = 934) samples from RCC patients and found a significant upregulation of CD248 expression (p < 0.001)." (PMID 34970489, 2021). "CD248 highly-expressed in tumor tissue, especially in BRCA, and it was related to the prognosis of patients." (PMID 33585235, 2020). "Biodistribution studies in xenograft-bearing mice confirmed high tumor uptake 89Zr-Ontuxizumab can be used to determine CD248 expression." (PMID 30847027, 2019). "The antibody–drug conjugate anti-CD248-MC-VC-PABC-MMAE, with 3–4 MMAE molecules per ADC, was selectively cytotoxic to CD248-positive cells in culture and produced profound, durable tumor control in human CD248-positive tumor xenografts." (PMID 30847027, 2019). "In vivo, ontuxizumab significantly affected syngeneic tumor growth and tumor metastasis in human CD248 knock-in mice." (PMID 30623276, 2019). "This technique resulted in rapid tumour uptake and real‐time visualisation of tumour burden and CD248 localisation in mice." (PMID 31287944, 2019). "CD248-TT vaccination elicited CD8+ cytotoxic T cell responses against tumor-specific antigens indicating that targeting CD248 has therapeutic potential in cancer immunotherapy." (PMID 30847027, 2019). "CD248 has been described as a tumor antigen suitable for chimeric antigen receptor (CAR) T cell therapy." (PMID 30847027, 2019). "For these reasons, there has been a substantial drive into developing innovative strategies of targeting CD248 for tumour therapy." (PMID 31287944, 2019). "Such prometastatic effects were attributed to CD248 expressing pericytes enhancing tumour cell intravasation." (PMID 31287944, 2019). "The murine ortholog of CD248 was cloned and found to be expressed during development and during implanted tumor growth in the adult mouse." (PMID 30847027, 2019). "The authors described CD4+ and CD8+ T‐cell clones that were specific for CD248 epitopes as well as tumour specific antigens." (PMID 31287944, 2019). "CD248 is a transmembrane glycoprotein that is dynamically expressed on pericytes and fibroblasts during tissue development, tumor neovascularization and inflammation." (PMID 30847027, 2019). "Specific CD248-positive tumor localization of the selected Fc-fusion protein was confirmed with optical imaging." (PMID 30847027, 2019). "MORab-004 treatment induces internalization of CD248 by pericytes, which coincides with a depolarization of both pericytes and ECs, suggesting that CD248 acts as a scaffold or guide for tumour microvasculature." (PMID 27916653, 2017). "Endosialin, also called Tumor Endothelial Marker-1 (TEM-1) or CD248 is one of several proteins that have been identified to be localized to the tumor stromal compartment." (PMID 27494870, 2016).
tumor (continued). "In this study, we have discovered that MORAb-004, via its target antigen internalization function, was able to create an effect similar to that of CD248-null mouse in regards to tumor neovasculature." (PMID 26327620, 2015). "So far only one publication demonstrated that CD248 is directly involved in tumor neovascularization." (PMID 26327620, 2015). "In order to test MORAb-004 biological activity on tumor growth we generated a human CD248 knock-in mouse line and evaluated the effect of MORAb-004 in syngeneic tumor models." (PMID 26327620, 2015). "Taken together, our results revealed a mode of action of MORAb-004 by which internalization and reduction of CD248 on pericytes impaired the initiation of tumor microvessels and ultimately suppressed tumor angiogenesis." (PMID 26327620, 2015). "In this report, the authors showed that in comparison with tumors in parental animals, tumor growth, invasion, and metastasis were drastically reduced in CD248 knockout mice." (PMID 26327620, 2015). "CD248 binds to extracellular matrix proteins fibronectin, collagens types I and IV, and it is thought that the interaction between these components and CD248 mediates cell attachment and migration during tumor progression." (PMID 26633297, 2015). "Tumors that grew in the knockout mice also showed abnormal blood vessel sizes and structure, suggesting that CD248 functionally governed the proper growth and formation of tumor vessels." (PMID 26327620, 2015). "When immunofluorescent staining was performed on B16-F10 sc tumor sections, human CD248 was found highly expressed on the outer layer cells of the neovasculature." (PMID 26327620, 2015). "It has been reported that expression of human CD248 is highly induced on the pericytes surrounding the newly formed tumor blood vessels." (PMID 26327620, 2015). "Studies in murine CD248 knockout mice had shown that CD248 played an essential role on tumor growth." (PMID 26327620, 2015). "Here, we report that MORAb-004 treatment significantly impacted syngeneic tumor growth and tumor metastasis in the human CD248 knock-in mice." (PMID 26327620, 2015). "Endosialin, also called Tumor Endothelial Marker-1 (TEM-1) or CD248, is one of several proteins that are localized to the tumor stromal compartment." (PMID 24980818, 2014). "Since the discovery of CD248, clinical and genetic evidence has pointed to it as a promoter of tumor growth and inflammation." (PMID 24555435, 2014). "Even BMP2 and activin, members of the TGFβ superfamily and pleiotropic cytokines that also exhibit tumor promoter and suppressor activities, had little effect on CD248 expression." (PMID 24555435, 2014). "We have shown that the tumor suppressor properties of TGFβ, observed in early stage cancer, are likely mediated in part via suppression of CD248, the latter which is mediated via canonical Smad-dependent pathways." (PMID 24555435, 2014). "Delineating the molecular mechanism(s) by which TGFβ loses its ability to suppress CD248 will be key for the design of additional therapeutic interventions to prevent and/or reduce CD248-dependent tumor cell proliferation and metastasis." (PMID 24555435, 2014). "This is consistent with the almost undetectable levels of CD248 in normal tissues, its expression presumably held in check at least in part by TGFβ’s tumor suppressor properties." (PMID 24555435, 2014). "Although the molecular mechanisms remain to be clarified, identification of strategies to downregulate CD248 will be important for the design of therapies to reduce both tumor growth and inflammation." (PMID 21549007, 2011). "The findings extend previous reports of the importance of CD248 in tumor growth and point to the cytoplasmic domain of CD248 as a potential therapeutic target in neoplasia." (PMID 21549007, 2011). "In breast cancer and neuroblastomas, CD248 expression levels have been directly correlated with tumor grade, invasiveness and poor prognosis." (PMID 21549007, 2011).
tumor (continued). "The cytoplasmic domain of CD248 is a critical enabler for stromal fibroblast activation, endowing the fibroblast with several tumor-promoting properties." (PMID 21549007, 2011). "Taken together, the findings support the concept that suppression of CD248 or interfering with signaling via its cytoplasmic domain may be associated with increased maturation of tumor stromal or perivascular fibroblasts and expression of tumor suppressor genes." (PMID 21549007, 2011). "This is relevant to CD248, as two groups have reported a CD248-dependent inverse relationship between microvessel density and size of tumor." (PMID 21549007, 2011). "Based on these data, we predicted that the highly conserved cytoplasmic domain of CD248 would mediate signals that critically contribute to tumor growth." (PMID 21549007, 2011). "Overall, our studies confirm that CD248 is an important central regulator of several critical pathways involved in stromal fibroblast migration, proliferation and activation that impact on tumor growth." (PMID 21549007, 2011). "CD248 was originally believed to be a tumor endothelial cell marker, and thus referred to as endosialin or TEM1." (PMID 21549007, 2011). "The variable contribution of CD248 to tumor growth highlights the importance of understanding and establishing multiple targets for the design of effective therapies for given tumors." (PMID 21549007, 2011). "The preceding studies underscore the role of the cytoplasmic domain of CD248 in modulating genes that regulate stromal fibroblast differentiation, maturation and migration and the expression of tumor suppressor genes." (PMID 21549007, 2011). "These suggest that CD248 is a specific tumor antigen, and targeting CD248 may exhibit on-target/off-tumor activity in pan-cancer." (PMID 40276611, 2025). "For example, several CD248-specific antibodies have been recently developed for tumor therapy, including monoclonal antibodies such as MORAb-004, hMP-E−8.3, and 3K2L, as well as single-chain variable fragments (scFv) such as scFv78, scFv78-Fc, scFv-CM6, scFv-1C1m, and scFv-7G22." (PMID 40276611, 2025). "Tumor endothelial marker 1 (endosialin/TEM-1/CD248) is found in many cell types, including endothelial cells, cancer cells, and CAFs, and is associated with promoting tumorigenesis and tumor angiogenesis." (PMID 40735646, 2025). "The differential expression of CD248 across various tumor types is influenced by multiple factors." (PMID 40276611, 2025). "CD248 is expressed across tumor stromal cells, especially fibroblasts and PCs." (PMID 40248695, 2025). "Second, the tissue origin of tumor may also influence CD248 expression, tumors derived from epithelial tissues demonstrate higher CD248 expression, whereas those of mesenchymal origin exhibit relatively lower expression." (PMID 40276611, 2025). "The findings demonstrated that CD248 plays a crucial role in tumor growth and patient prognosis, indicating that CD248 could be an immunotherapeutic target for pan-cancer in the future." (PMID 40276611, 2025). "In addition, novel CAR T-cell strategies such as armored CAR T-cells targeting vascular endothelial protein, CD248, can significantly inhibit tumor growth and metastasis by specifically attacking tumor-associated pericytes." (PMID 41226585, 2025). "Furthermore, the pathological assessment revealed that higher levels of CD248 (p = 0.0173) and PD-L1 (p = 0.0434) were positively correlated with the advanced tumor–node–metastasis (TNM) stage." (PMID 40735646, 2025). "A recent study revealed that CD248 could suppress Wnt signaling and upregulates the expression of Osteopontin (OPN) and SERPINE1, which are associated with increased tumor volume." (PMID 40248695, 2025). "Interestingly, αSMA expression was also significantly reduced after antibody blockade, a potential corollary to the heightened degree of tumor vessel dysfunctional after CD248 mAb blockade." (PMID 38468017, 2024).